IL6 (interleukin 6)
Diseases named in the same sentence as IL6 in open-access papers (continued):
Sharing a sentence is not in itself a finding about the gene and the disease.
pulmonary fibrosis (continued). "IL-6, which is expressed in type II alveolar epithelial cells and M1 macrophages, is associated with lung fibrosis through the polarization of M2 macrophages." (PMID 34719405, 2021). "The IL-6 level in the acute stage and albumin level were independent risk factors for pulmonary fibrosis." (PMID 33755708, 2021). "In our study, similar to others, inflammatory factors including IL-6, TNFα, and related factors associated with pulmonary fibrosis were reduced, including TGF-β and IFN-γ." (PMID 34271988, 2021). "Our results showed that there were significant relationships between pulmonary fibrosis and the levels of albumin and IL-6, which suggests that IL-6 and albumin are independent risk factors affecting pulmonary fibrosis." (PMID 33755708, 2021). "Fisetin treatment causes a reduction of the transcription level of IL-6 in senescent cells in pulmonary fibrosis and aging-related pathology." (PMID 34804003, 2021). "Levels of cytokines, such as tumor necrosis factor-alpha (TNF-α) and interleukin-6, are increased with IR and cause lung fibrosis and inflammation." (PMID 33794844, 2021). "B cell-specific IL-6 deficient mice showed attenuated skin and lung fibrosis upon bleomycin challenge, suggesting a pathogenic role of B cell-derived IL-6 in the scleroderma model." (PMID 32708044, 2020). "A previous study using IL-6-/- mice showed deficiency in the development of a profibrogenic response, thereby highlighting the importance of IL-6 in bleomycin-induced pulmonary fibrosis." (PMID 31765381, 2019). "Specifically, there was a reduction in alternatively activated macrophages, IL-6, and hyaluronan, all of which have been implicated in pulmonary fibrosis and pulmonary hypertension." (PMID 31379836, 2019). "Elevated adenosine levels were seen in association with elevated IL-6 and interleukin 17 (IL-17) levels, which have been shown to be crucial inflammatory, pro-fibrotic mediators in pulmonary fibrosis." (PMID 31379836, 2019). "Regarding the ADORA2B mediated mechanisms, our data showed that activation of ADORA2B in PASMCs leads to increased levels of IL-6 and hyaluronan, two mediators that have been associated in the pathophysiology of lung fibrosis and PH." (PMID 29910735, 2018). "Interleukin 6 (IL-6) is an inflammatory cytokine and its inhibition is linked with reduced lung fibrosis." (PMID 29854623, 2018). "In the lung of COPD patients, the cytokine IL-6 is suggested as one of the main inducers causing lung fibrosis and lung tissue remodeling." (PMID 30258361, 2018). "To explore the role of IL-6 in the pathogenic mechanism of PQ-induced pulmonary fibrosis, we tested the levels of EMT-related genes in epithelial cells." (PMID 28194150, 2016). "The purpose of this study was to explore the effect of IL-6 on PQ-induced pulmonary fibrosis and further to interpret its underlying mechanisms." (PMID 28194150, 2016). "Several members of the IL-6 cytokine family, which is characterized by the shared use of the common gp130 receptor subunit, have been implicated in pulmonary fibrosis." (PMID 22684844, 2012). "Results from our study also demonstrate that IL-6 contributes to pulmonary fibrosis in ADA-deficient mice." (PMID 21799929, 2011). "Serum NT-proBNP hs-CRP and IL-6 concentrations were quantified by enzyme-linked immunosorbent assay (ELISA), while chest computed tomography(CT) manifestations were evaluated using the AcuteExacerbation of Idiopathic Pulmonary Fibrosis (AE-IPF)scoring system." (PMID 41799712, 2026). "Studies on A. cantonensis in rats have shown that IL-6 upregulation was associated with persistent pneumonia in early infection and lung fibrosis in later stages, mediated through the IL-6/Stat3 pathway, which enhances inflammatory processes and leads to structural damage in lung tissue." (PMID 40529303, 2025).
pulmonary fibrosis (continued). "In patients with severe disease, fibrosis-related cytokines such as Transforming Growth Factor (TGF-β), Tumor Necrosis Factor (TNF-α), and Interleukin (IL)-6 are significantly elevated in peripheral blood, which is closely associated with the development of pulmonary fibrosis." (PMID 40427668, 2025). "TNF-α increases the risk of pulmonary fibrosis by inducing the expression of IL-1, IL-6, and IL-8." (PMID 38515835, 2024). "Aditionally, our analysis revealed that the increase in IL-6 at the 3-month evaluation represents a risk factor for lung fibrosis, while the risk of fibrosis in both timelines (3 months and 2 years) was found to also be proportional to the values of inflammatory markers (ESR and fibrinogen)." (PMID 39767173, 2024). "Herein, we demonstrate in mouse models of lung damage following exposure to ionizing radiation that opaganib significantly improved long-term survival associated with reduced lung fibrosis, suppression of granulocyte infiltration, and reduced expression of IL-6 and TNFα at 180 days after radiation." (PMID 38396999, 2024). "IL-6 levels were reported to be slightly elevated in a rat model of experimental pulmonary fibrosis, which was linked to a proliferative response in fibroblasts from idiopathic pulmonary fibrosis (IPF)." (PMID 39600959, 2024). "IL-6, produced by abnormal immunity, may cause pulmonary fibrosis, vascular disease, and psychological disorders, even at fatigue onset." (PMID 38062429, 2023). "Moreover, the classical WNT/β-catenin pathway regulates inflammatory cytokines (TNF, IL-1, IL-6, IL-8, and IL-15), which play important roles in reducing lung inflammation and pulmonary fibrosis and are linked to the pathogenesis of BPD." (PMID 37180448, 2023). "Interestingly, a study using a bleomycin-induced model of scleroderma highlighted how B cell-specific IL-6 deficient mice had attenuated skin and lung fibrosis whilst B cell-specific IL-10-deficient mice had more severe fibrosis." (PMID 36726987, 2022). "On the other hand, another important pathogenic mechanism involved in the development of pulmonary fibrosis is the enhancement of IL-6 trans-signaling via ADAM-17 by activated macrophages, which increases the extracellular matrix deposits and the proliferation of fibroblasts." (PMID 35203527, 2022). "A higher intensity of the inflammatory process, associated with higher levels of CRP and IL-6 in patients, might lead to lung fibrosis during recovery." (PMID 36010377, 2022). "Our results showed that IL-6 is an independent risk factor for pulmonary fibrosis." (PMID 33755708, 2021). "Many previous studies showed that lung tissues accumulate excessive amounts of the inflammatory cytokines, TNF-α and IL-6, which cause damage to lung cells, and might also induce the development of lung fibrosis." (PMID 32244835, 2020). "Similarly, Arpin and coworkers found that high levels of IL-10 were protective against radiation induced symptomatic pulmonary fibrosis after thoracic radiotherapy, while elevation of IL-6 was associated with more severe lesions." (PMID 22216271, 2011). "IL-6 may modulate pulmonary inflammation as supported by the observation that an increased IL-6 level in BAL fluid was associated with lung fibrosis in human and animal models." (PMID 20302663, 2010). "The IL-6 trans-signaling pathway, involving soluble IL-6 receptor (sIL-6R), is essential for driving collagen production and fibrotic changes, as demonstrated in murine models where IL-6 signaling caused SS-like symptoms such as pulmonary fibrosis and skin thickening." (PMID 41009491, 2025). "In addition, previous research has shown that Aptamin C more effectively suppresses the pro-inflammatory cytokines IL-1α and IL-6 than vitamin C, demonstrating that it may play a role in managing inflammation associated with pulmonary fibrosis." (PMID 39770419, 2024).
pulmonary fibrosis (continued). "In addition, persistent inflammation, lung fibrosis, and damage to pulmonary vasculature caused by pro-inflammatory cytokines such as IL-6 may potentially contribute to long-term respiratory symptoms." (PMID 38231284, 2024). "In BLM-induced rats, WYLG granules significantly alleviated pulmonary fibrosis, reduced inflammatory cell infiltration and collagen deposition, downregulated IL-6 and α-SMA levels, and upregulated E-cadherin expression." (PMID 41737799, 2026). "Inhibition of lung injury healing, promotion of lung cell death, and eventual induction of pulmonary fibrosis can be caused by TGF-β1, IL-1β, IL-6, and TNF-α." (PMID 40665395, 2025). "Previous research has explored various strategies for inhibiting IL-6 signaling in fibrotic diseases such as idiopathic pulmonary fibrosis and peritoneal fibrosis." (PMID 40853309, 2025). "In models of radiation‐induced pulmonary fibrosis, atRA inhibited IL‐6 production through a protein kinase C (PKC)‐δ/NF‐κB–mediated mechanism." (PMID 40031928, 2025). "The bipartite APNet graph contained a large community connecting several drivers (IL6–JUN–CCL7–MAPK9–POLR2F–HSPA1A–BAX–TRIAP1), associated with interleukin signalling (IL4/13/17/18), cytokine stimulation, liver disease, and lung fibrosis." (PMID 39921901, 2025). "In BLM-induced pulmonary fibrosis, it has been reported that early suppression of IL-6 worsens fibrosis, while late suppression improves it." (PMID 41323794, 2025). "Lung and circulating IL-6 levels increased in mice after exposure to CAPs, and IL-6 plasma levels correlated with PM exposure in humans, potentially providing a link between exposure, epithelial remodeling, and lung fibrosis." (PMID 40892514, 2025). "The levels of TNF-α, IL-1β, and IL-6 expression were enhanced in PM10-induced pulmonary fibrosis (p < 0.05)." (PMID 40299673, 2025). "IL-6 has a well-established role in mediating skin and lung fibrosis in SSc, and treatment with tocilizumab has provided to be beneficial for SSc-ILD." (PMID 39802335, 2025). "Increased levels of IL-6 have been also associated with a poorer outcome in IPF patients, underlining its potential as an emerging target strategy to treat lung fibrosis." (PMID 41155824, 2025). "Vesicles from Akkermansia muciniphila reduce IL-6 production and increase IL-10 secretion, thereby alleviating carbon tetrachloride-induced pulmonary fibrosis in mice." (PMID 41304154, 2025). "Resveratrol effectively inhibits alveolar epithelial cell senescence and ameliorates pulmonary fibrosis, likely by targeting key senescence-associated pathways (e.g., SERPINE1, MMP2, IL-6)." (PMID 41383484, 2025). "Aqueous extract of CGE also alleviated bleomycin-induced idiopathic pulmonary fibrosis in rat model, which related to the reduction of IL-6, IL-8, TGF-β1, and so on." (PMID 38974913, 2024). "In paraquat-induced pulmonary fibrosis, elevated IL-6 expression depends on acetylation of H3K9ac in the IL6 promoter region." (PMID 38473997, 2024). "For example, prolonged elevated levels of MIP1α and MCP-1 promote chronic lung fibrotic disease while IL-6 is an important driver of bleomycin-induced lung fibrosis in mice." (PMID 38509617, 2024). "In fact, IL-6 promotes pulmonary fibrosis and respiratory dysfunction and can also inducer intrarenal inflammation, myocardial fibrosis, and kidney and gastrointestinal damage." (PMID 38010585, 2024). "WISP1 is involved in impaired epithelial–mesenchymal crosstalk in pulmonary fibrosis, induces IL6 expression, and promotes pro-proliferative effects on fibroblasts." (PMID 38534359, 2024). "Research conducted by Ying-Wei Lan showed that, compared with mice with induced pulmonary fibrosis, the group treated with Kefir yogurt showed a notable downregulation of pro-inflammatory factors such as IL-4, IL-6, and TNF-α." (PMID 39683559, 2024).
pulmonary fibrosis (continued). "For example, nintedanib treating idiopathic pulmonary fibrosis can reduce the expression of proinflammatory factors IL-1β, IL-6, and TNF-ɑ by downregulating the PI3K/Akt/mTOR pathway." (PMID 39108701, 2024). "Next, we investigated the effect of IL6 on STAT3 activation, a canonical transcriptional mediator of IL6 downstream signaling and promoter of pulmonary fibrosis." (PMID 38650935, 2024). "It is also indicated by high levels of complement protein C1q and myofibroblasts, which are differentiated from fibroblasts by IL-6, in patients with pulmonary fibrosis." (PMID 39684535, 2024). "The lung tissue levels of IL-6, osteopontin, IFNγ, and SP-D were significantly lower in the TG group with lung fibrosis than in their WT counterparts." (PMID 39329706, 2024). "In the acute lung injury model, NKS3 decreased lung fibrosis and inflammatory cytokines (IL-1β, IL-6 and TNF-α) and nitric oxide (NO) production in broncho-alveolar lavage fluid." (PMID 38598021, 2024). "An important contribution of certain cytokines, such as IL-17A, IL-6, and IL-8 in pulmonary fibrosis has been observed." (PMID 38263193, 2024). "IL-6 is a pleiotropic cytokine and functions as a pro-inflammatory factor and a profibrotic factor in lung fibrosis pathogenesis." (PMID 39596365, 2024). "To characterize the kinetic effects of 2 U/kg i.t. bleomycin on various biochemical markers of lung fibrosis, we measured the concentrations of TGFβ1, IL6, TNFα, IL1β, CINC1, WISP1, VEGF, and TIMP1 in BALF at days 3, 7, and 14 following instillation." (PMID 38534359, 2024). "For pulmonary fibrosis, a positive feedback loop where elevated NEU3 causes upregulation of the profibrotic extracellular signals TGF-β1 and IL-6, and TGF-β1 and IL-6 upregulate NEU3, appears to participate in fibrosis." (PMID 39570922, 2024). "The modified KuShen–GanCao formula (mKG) was shown to suppress inflammation and pulmonary fibrosis and decreased the levels of IL-6, IL-17, and TGF-β in the lungs of mice with asthma." (PMID 38074219, 2023). "Interleukin-6 (IL-6) in individuals with idiopathic pulmonary fibrosis have been demonstrated to be reduced with ACT001." (PMID 37978497, 2023). "Consistent with the earlier studies, we found that overexpression of Sestrin2-inhibited ROS production and the level of TNF-α, IL-6, and IL-1β to attenuate endoplasmic reticulum stress and ferroptosis, thereby ameliorating lung fibrosis." (PMID 38023615, 2023). "Serum levels of IL-6 strongly correlate with the severity of SSc lung fibrosis and are predictive of mortality in SSc patients, suggesting a profibrotic role of IL-6 in lung tissues." (PMID 36769282, 2023). "It is noteworthy that IL-6 has been shown to have pleiotropic effects that can be antifibrotic or pro-fibrotic, and pro-inflammatory in bleomycin-induced lung fibrosis in mice." (PMID 36678611, 2023). "In this regard, it is worth noting that the blocking IL-6 is shown to attenuate pulmonary fibrosis in mice." (PMID 38081956, 2023). "Another group described positive correlations between serum levels of IL-6 and IL-10 and mRSS, together with a positive relation between IL-10 and pulmonary fibrosis." (PMID 37833885, 2023). "In particular, during the initial phases of the fibrotic process, NF-κB increases the expression of genes coding for the synthesis of many inflammatory cytokines, such as TNFα, IL6, IL1β and TGFβ, essential for the development of pulmonary fibrosis." (PMID 37626373, 2023). "CD36-null cells have increased expression of LPL, IL-6 and IL1-β which have been implicated in inflammasome assembly during bleomycin induced pulmonary fibrosis." (PMID 38098035, 2023). "The capacity of IL-6 trans-signaling to drive fibrosis has been analyzed in mouse models of skin and lung fibrosis." (PMID 37669366, 2023).
pulmonary fibrosis (continued). "There was found a significant increase in the BAL fluid levels of IL-4, IL-6, IL-7, and IL-8, and a significant relationship with pulmonary fibrosis in the patients, hence the role of BAL fluid cytokines in ILD pathophysiology." (PMID 37670355, 2023). "Similar to the long COVID patients with pulmonary symptoms, elevated levels of IL-6, CRP, and TGF-β were identified in patients at increased risk of developing pulmonary fibrosis after SARS-CoV-2 infection." (PMID 36744129, 2023). "Histone H3 acetylation was reported to contribute to the overexpression of profibrotic cytokine interleukin-6 in paraquat-induced pulmonary fibrosis." (PMID 37312162, 2023). "Surprisingly, they identified that blockade of PD-L1, CD47, and IL-6 significantly alleviated the severity of pulmonary fibrosis not only in bleomycin-induced pulmonary fibrosis mice model but in IL-6 knockout and humanized NSG mice models." (PMID 36544757, 2022). "Consistent with the PD-L1 expression level in the lung tissue of the bleomycin-driven pulmonary fibrosis murine model, Cui and colleagues observed that PD-L1 was also positively expressed in the lung of IL-6 knockout mice." (PMID 36544757, 2022). "The overactivation of C/EBPγ induced by IL-1β inhibits IL-6 expression in lung epithelial cells, which indirectly suppresses lung fibrosis." (PMID 36299447, 2022). "The Jak−STAT pathway is activated by several cytokines, such as IL-6, IL-4, IL-13, and TGF-β, which are implicated in the pathogenicity of pulmonary fibrosis." (PMID 36556326, 2022). "At the onset of pulmonary fibrosis, M2 macrophages induce fibroblasts to secrete IL-6, which counteracts fibroblasts, induces their activation, and promotes the occurrence of pulmonary fibrosis." (PMID 36422524, 2022). "Overall, our study implicates the low-diversity gut microbiota as a contributor of pulmonary fibrosis severity through their capacity to activate the IL-6/STAT3/IL-17A signaling pathway." (PMID 36543914, 2022). "Honokiol can inhibit TGF-β/Smad signaling, matrix proteins, and the IL-6/CD44/STAT3 axis to reduce pulmonary fibrosis, which exerts anti-inflammatory and antioxidant effects." (PMID 36588723, 2022). "Decreases collagen I and III expression, serum TGF-β1 content and alveolar lavage fluid IL-6 levels and effectively improves bleomycin-induced pulmonary fibrosis in mice." (PMID 35566359, 2022). "Following the statistical analysis, the authors found significantly higher levels of IL-6 in the early SS form compared to the control arm, with high levels found especially in patients with pulmonary fibrosis." (PMID 35203527, 2022). "IL-6 deficiency ameliorated skin and lung fibrosis induced by TOPO-I, suggesting that fibrosis in this immunization model is IL-6 dependent." (PMID 35837382, 2022). "IL-6 levels, especially in early SS with mild forms of pulmonary fibrosis, appear to have a prognostic value for impaired lung function and increased mortality." (PMID 35203527, 2022). "The distinctions in the percentages of CD4 + IL-6+ and CD4 + IL-17A + T cells among mice in different housing cohorts support microbiota-induced alterations to the IL-6/ STAT3/IL-17A pathway in pulmonary fibrosis." (PMID 36543914, 2022). "They proved that PNS can reduce AST, LDH, CK, IL-6, and IL-8 in rabbit serum by inhibiting the NF-κB signaling pathway and mitigate pulmonary fibrosis." (PMID 35865337, 2022). "The profibrotic effects of IL-6 in pulmonary fibrosis have also been observed, which suggests the potential contribution of IL-6 in the fibrotic changes in the chronic phase of CIP." (PMID 35967342, 2022). "For instance, the mechanism of action of PNS in the treatment of pulmonary fibrosis was studied, and the expression of IL-6 and IL-8 in the PNS group was significantly decreased." (PMID 35865337, 2022).